SPON1 (spondin 1)
Description:
Cell adhesion protein that promotes the attachment of spinal cord and sensory neuron cells and the outgrowth of neurites in vitro. May contribute to the growth and guidance of axons in both the spinal cord and the PNS (By similarity). Major factor for vascular smooth muscle cell.
Synonyms: KIAA0762; f-spondin; VSGP/F-spondin
Tractability: Small molecule: it has a high-quality binding pocket. Antibody: UniProt places it where antibodies can reach, with medium confidence; UniProt predicts a signal peptide or a membrane-spanning region; its Gene Ontology location is reachable by antibodies, with medium confidence. PROTAC: its protein half-life has been measured.
Gene: Protein-coding gene on chromosome 11 (13,962,694 to 14,268,133, forward strand). Ensembl gene ENSG00000262655.
Subcellular location: Secreted, extracellular space, extracellular matrix
Subcellular location (Human Protein Atlas): Vesicles; Predicted to be secreted
Pathways (Reactome):
Disease: Defective B3GALTL causes PpS
Metabolism of proteins: O-glycosylation of TSR domain-containing proteins
Gene Ontology:
Molecular function: protein binding; extracellular matrix structural constituent; LBD domain binding
Biological process: cell adhesion
Cellular component: extracellular matrix; extracellular region; endoplasmic reticulum lumen
Genetic constraint (gnomAD): Loss-of-function variants: 51 observed, 93.77 expected, observed/expected ratio (o/e) 0.54, 90% interval 0.43 to 0.69. The upper end of that interval is the gene's LOEUF score, 0.69, which puts it in group 2 of 6, group 1 being the genes least tolerant of losing a copy. Missense variants: 928 observed, 995.77 expected, observed/expected ratio (o/e) 0.93, 90% interval 0.88 to 0.98. Synonymous variants: 399 observed, 360.55 expected, observed/expected ratio (o/e) 1.11, 90% interval 1.02 to 1.2.
Homologues: Orthologues: chimpanzee SPON1 (99% identical), macaque SPON1 (99% identical), dog SPON1 (98% identical), pig SPON1 (98% identical), rat Spon1 (97% identical), guinea pig SPON1 (96% identical), mouse Spon1 (96% identical), rabbit SPON1 (96% identical), tropical clawed frog spon1 (84% identical), zebrafish spon1a (77% identical), Drosophila melanogaster CG17739 (33% identical), Caenorhabditis elegans spon-1 (31% identical), and 2 more. Paralogues in human: THSD7A (27% identical), THSD7B (24% identical), SPON2 (13% identical).
Diseases named in the same sentence as SPON1 in open-access papers:
SPON1 is named in the same sentence as 67 diseases in open-access papers, as found by Europe PMC text mining. Sharing a sentence is not in itself a finding about the gene and the disease. The quoted sentences say what the papers report.
Alzheimer disease (8 papers, 2015 to 2025). A progressive, neurodegenerative disease characterized by loss of function and death of nerve cells in several areas of the brain leading to loss of cognitive function such as memory and language. "SPON1 encodes for the spondin 1 protein that has been previously associated with Alzheimer's disease (AD) and dementia." (PMID 35277195, 2022). "Recent genome-wide association studies of the rate of cognitive decline in Alzheimer’s disease indicated SPON1 as candidate gene associated with slower rate of cognitive decline in Alzheimer’s disease." (PMID 32131477, 2020). "For example, we found that SPON1 and RRAS2, overrepresented specifically in L-RG HES5+ cells and thus may relate to gliogenesis, contain SNPs associated with Alzheimer’s disease (P=2.07E−4, Odds=15.26)." (PMID 25799239, 2015). "Although this exact pathway did not emerge from our analyses, we did find associations for SPON1 and IGFBP7 and similar Alzheimer’s disease-related pathways in protein glycosylation and ether lipid metabolism, confirming the relevance of these pathways." (PMID 41280530, 2025).
osteosarcoma (8 papers, 2017 to 2024). A usually aggressive malignant bone-forming mesenchymal neoplasm, predominantly affecting adolescents and young adults. "SPON1 has also been found to increase osteosarcoma cell motility through an Fak/Src-dependent pathway." (PMID 38716730, 2024). "SPON1 upregulation is closely related to metastasis and progression of osteosarcoma, promoting migration and invasion of osteosarcoma cells in vivo and in vitro, as well as activating FAK (PTK2) and SRC in osteosarcoma cells." (PMID 36520032, 2023). "Previous studies showed that SPON1 triggers focal adhesion kinase 1 (Fak) and tyrosine‐protein kinase Src signalling and promotes distant metastasis in osteosarcoma." (PMID 35487760, 2022). "There was evidence from a previous study that increased phosphorylated form of FAK and Src via activation by the extracellular matrix glycoprotein, Spondin 1, promoted cell invasiveness and pulmonary metastatic progression of osteosarcoma." (PMID 28846700, 2017). "In other cancer types, SPON1 promotes the metastasis of human osteosarcoma, while methylated BHLHE22/CDO1/CELF4 panel could be used for endometrial cancer screening." (PMID 33860722, 2021). "For instance, the cell adhesion protein Spondin 1 also promotes cell migration and invasion through FAK and Src activation in human osteosarcoma cell lines, and Src is well known to be increase cell permeability, EMT, migration, invasion and metastasis of tumor cells." (PMID 31671408, 2019).
cognitive decline (5 papers, 2018 to 2025). "Genetic variation in SPON1 has been linked to the rate of cognitive decline in AD53,54." (PMID 37550416, 2023).
dementia (5 papers, 2014 to 2024). Loss of intellectual abilities interfering with an individual's social and occupational functions. "Spon1 is a novel candidate gene for hypertension and its polymorphism is associated with severity of dementia." (PMID 24667548, 2014). "SPON1 is an matricellular protein that structurally consists of 6 thrombospondin domains, one spondin domain, and one reelin domain, and has been primarily implicated in dementia and axonal development." (PMID 38225249, 2024).
hepatocellular carcinoma (5 papers, 2022 to 2026). A malignant tumor that arises from hepatocytes. "Overexpression of miR‐506 suppressed hepatocellular carcinoma both in vitro and in vivo and reduced the accumulation of SPON1 both in hepatocellular carcinoma (HCC) cells and mouse tissues." (PMID 36520032, 2023). "In hepatocellular carcinoma, microRNA‐506 binds to SPON1 to inhibit cell proliferation, migration and invasion." (PMID 36354023, 2022). "In hepatocellular carcinoma (HCC), METTL6 depletion inhibits cell growth, colony formation, migration, invasion, and cell adhesion and reduces the expression levels of cell adhesion proteins such as ITGA1, SPON1, and CLDN14." (PMID 41501031, 2026).
Hypertension (5 papers, 2014 to 2024). The presence of chronic increased pressure in the systemic arterial system. "Animal models implicate SPON1 in genetically mediated hypertension and in cardiac remodeling due to ischemia-reperfusion, consistent with our MR results supporting a causal association of SPON1 with hypertension and atrial fibrillation." (PMID 38225249, 2024). "Among these up-regulated genes, Spon1, which is a previously identified candidate gene for hypertension, was found to be up-regulated in kidney of human with diabetic nephropathy." (PMID 24667548, 2014). "In this rat model, the Spon1 gene was also identified as a novel candidate gene for hypertension." (PMID 33439866, 2021). "We observed MR evidence for associations between genetically regulated levels of 7 proteins and HF risk factors including: SPON1, CCL15, and ITIH3 with hypertension; SVEP1 and SPON1 with atrial fibrillation; FSTL3 and NRP1 with diabetes; and APOF, CCL15, ITIH3, and NRP1 with CHD." (PMID 38225249, 2024). "Further adjustment for diabetes and hypertension did not substantially attenuate hazard ratios for ANGPT2, Spondin-1, TRAP5 or NOTCH1." (PMID 30557359, 2018).
ovarian carcinoma (5 papers, 2019 to 2023). A malignant neoplasm originating from the surface ovarian epithelium. "Using this SPON1 mAb, we demonstrated that the RFS in the SPON1-high group of ovarian cancer subjects is significantly lower than that in the SPON1-low group, and that high SPON1 expression is associated with various clinicopathological factors." (PMID 37179355, 2023). "In the present study, we focused on the secreted protein spondin-1 (SPON1) and clarified the prognostic relevance in ovarian cancer." (PMID 37179355, 2023). "SPON1 appeared to be observed in the cytoplasm of ovarian cancer tissues, but its signal intensity (SI) and percentage of positive cells (PP) were different among subjects." (PMID 37179355, 2023). "Out of 242 cases of ovarian cancer tissues, we showed that SPON1 was weakly, moderately, and strongly expressed in 87 (36.0%), 64 (26.4%), and 22 (9.1%), respectively." (PMID 37179355, 2023). "In summary, the present study highlighted that high SPON1 expression predicts poor prognosis of ovarian cancer." (PMID 37179355, 2023). "Multivariable analysis revealed that high SPON1 was an independent prognostic factor for RFS of ovarian cancer." (PMID 37179355, 2023). "Taken together with previous report, these results suggest that SPON1 represents a specific biomarker for ovarian cancer." (PMID 37179355, 2023). "On the other hand, upon searching the CCLE, SPON1 mRNA was highly expressed not only in ovarian cancer cell lines but also in endometrial cancer cells." (PMID 37179355, 2023). "We also concluded that high SPON1 expression represents an independent poor prognostic marker for ovarian cancer at time of initial surgery." (PMID 37179355, 2023). "While SPON1 expression is found in malignancies including ovarian cancer, the effect of SPON1 depends on the cancer type." (PMID 35054873, 2022). "Spondin 1 (SPON1) has been identified as a potential biomarker of ovarian cancer, and also downregulated during cutaneous melanoma development." (PMID 30867659, 2019). "Thus, analysis of a large number of cases will be required to obtain more solid conclusions on the clinicopathological relevance of the high SPON1 expression in patients with ovarian cancer." (PMID 37179355, 2023). "SPON1 represents a prognostic biomarker for ovarian cancer, and the anti-SPON1 mAb could be valuable as an outcome predictor." (PMID 37179355, 2023). "In addition, it recognized the endogenous SPON1 signals in three ovarian cancer cell lines by immunohistochemistry using their cell blocks." (PMID 37179355, 2023). "Interestingly, SPON1 was also occasionally observed in stromal cells of SPON1-positive ovarian cancer tissues." (PMID 37179355, 2023). "Taken collectivity with the notion showing that SPON1 is a secreted protein, it is reasonable that SPON1 could be used as a serum biomarker for ovarian cancer and STIC." (PMID 37179355, 2023). "These SPON1-positive signals were distributed in the cytoplasm, whereas SPON1 was concentrated not only in the cytoplasm but also on cell membranes of ascites-derived ovarian cancer cells." (PMID 37179355, 2023). "Further studies are also needed to determine whether and how SPON1 is involved in ovarian cancer progression as well as whether SPON1 can be used as a serum biomarker for ovarian cancer." (PMID 37179355, 2023). "By contrast, upon semi-quantification, 22 of 242 ovarian cancer cases (9.1%) exhibited high SPON1 expression, whereas 64 (26.4%), 87 (36.0%), and 69 (28.5%) cases, which were designated as SPON1-low, possessed the moderate, weak, and negative SPON1 expression, respectively." (PMID 37179355, 2023). "In addition, although SPON1 overexpression appeared to be basically restricted to ovarian cancer tissues, there are a few reports revealing that SPON1 promotes progression of other cancer types in vitro." (PMID 37179355, 2023).
ovarian carcinoma (continued). "In line with the putative tumor-promotive function of SPON1-TRIM29 fusion protein, it may be relevant to dissect each function of SPON1 or TRIM29 in ovarian cancer." (PMID 35054873, 2022). "Furthermore, SPON1 was distributed not only in the cytoplasm but also along cell membranes in ascites-derived tumor cells (cytokeratin-positive and D2-40-negative) obtained from a patient with ovarian cancer." (PMID 37179355, 2023). "Furthermore, we also showed that high SPON1 is an independent prognostic marker for ovarian cancer." (PMID 37179355, 2023). "Additionally, SPON1-expressing CAFs might also influence on ovarian cancer advancement." (PMID 37179355, 2023). "Next, by immunohistochemical analysis using the established mAb, we evaluated the expression of SPON1 protein in normal ovary, serous tubal intraepithelial carcinoma (STIC), and ovarian cancer tissues, as well as in a range of normal adult tissues." (PMID 37179355, 2023). "On the other hand, no SPON1 signal was detected in stromal cells of SPON1-negative ovarian cancer tissues." (PMID 37179355, 2023). "As describe above, SPON1 protein could be expressed in both STIC and ovarian cancer, while it was hardly detected in the normal tissues examined." (PMID 37179355, 2023). "Two fusion genes SPON1-NRG2α and SPON1-TRIM29, though which is observed with extremely low frequency, have been recently identified in ovarian cancer, suggesting the contribution of SPON1 in the pathogenesis of ovarian cancer." (PMID 37179355, 2023). "Nevertheless, the clinicopathological relevance of SPON1 protein expression in ovarian cancer has not been clarified so far, likely due to the absence of selective antibodies." (PMID 37179355, 2023). "SPON1 mRNA appeared to be highly expressed in ovarian cancer but not in other malignant tumors." (PMID 37179355, 2023). "The utility of SPON1 alone or together with CA-125 and/or Human epididymis protein 4 (HE4) should be determined in future experiments using serum samples from patients with ovarian cancer, other benign and malignant tumors, as well as samples from healthy individuals." (PMID 37179355, 2023). "In addition, SPON1 mRNA was highly expressed in ovarian cancer tissues but not in other malignant tissues or various normal tissues, which was in good agreement with the results of a previous report." (PMID 37179355, 2023). "In addition to PAX8, COPA complemented with pan-cancer analysis prioritized eight other lineage-restricted outliers (CDH6, CLDN16, FGF18, FOLR1, SLC34A2, SOX17, SPON1, WNT7A) displaying largely confined gene expression in ovarian cancer cell lines and tumor specimens." (PMID 31050342, 2019). "Thus, SPON1 could be promising as a specific protein biomarker for STIC and ovarian cancer." (PMID 37179355, 2023).
prostate carcinoma (5 papers, 2009 to 2023). A carcinoma that arises from epithelial cells of the prostate gland. "We found that SPOCK3 and SPON1 were significantly associated with prostate cancer patients’ PFS." (PMID 29190897, 2017). "The 2ME-loaded zeolite nanoparticles also decreased the viability and increased the mRNA of the 2ME-target gene F-spondin, encoded by SPON1, in the human prostate cancer cell line LNCaP." (PMID 37446151, 2023). "Forty-one candidates were all down-regulated in the first cohort of them, SPOCK3, SPON1, PTN and TGFB3 were associated with the prognosis of prostate cancer patients." (PMID 29190897, 2017). "We found that SPOCK3, SPON1, PTN and TGFB3 were significantly correlated with the progression-free survival (PFS) status of prostate cancer patients." (PMID 29190897, 2017). "Four genes (SPOCK3, SPON1, PTN and TGFB3) and a micro-RNA were selected for exploring their potential roles in the progression of prostate cancer." (PMID 29190897, 2017).
bladder cancer (4 papers, 2020 to 2023). "Previous studies have shown that overexpression of SPON1 was linked to poor OS in bladder cancer patients, GC cohort and in a PC cohort." (PMID 36354023, 2022). "In conclusion, high expression of ADRA2A, CXCL12, S1PR1, ADAMTS9, F13A1, and SPON1 was associated with poor overall survival in bladder cancer patients, with a P-value <0.05 considered to be statistically significant." (PMID 32239176, 2020). "The analysis showed that TNXB was upregulated in patients with bladder cancer (BLCA), cervical cancer (CESC), colon cancer (COAD), and breast cancer (BRCA), while SPON1 was upregulated in patients with LNM in thyroid cancer (THCA) and bladder cancer." (PMID 36520032, 2023).
endometrial cancer (4 papers, 2019 to 2024). Primary or metastatic malignant neoplasm involving the endometrium (mucous membrane that lines the endometrial cavity). "A single publication utilizing the E2 metabolite 2-methoxyestradiol (2-ME), which binds poorly to the nuclear ER, showed increased expression of SPON1 in endometrial cancer cell lines." (PMID 39598420, 2024).
heart failure (3 papers, 2018 to 2024). Inability of the heart to pump blood at an adequate rate to meet tissue metabolic requirements. "The prognostic associations of NOTCH1 and Spondin-1 were attenuated after adjustment for history of heart failure, but remained significant at p<0.01." (PMID 30557359, 2018). "From the same study, it was recently reported that 9 proteins (GDF-15, TIM-1, TRAIL-R2, SPON1, MMP-12, follistatin [FS], soluble urokinase-type plasminogen activator surface receptor [sU-PAR], OPG, and sST2) were associated with the development of heart failure." (PMID 33439866, 2021).
amyloid (2 papers, 2020 to 2024). "In our experiments, virus-mediated SPON1 was injected into young AD mice (three months old) to prevent Aβ plaque deposition from an early stage of amyloid pathology." (PMID 32455709, 2020).
cervical cancer (2 papers, 2018 to 2023). A primary or metastatic malignant neoplasm involving the cervix. "Notably, PEG3, SPON1, BTD and RPLP2 passed the defined threshold of FDR <0.25, indicating the potential of these genes in showing their significances in cervical cancer." (PMID 30065881, 2018).
chondrosarcoma (2 papers, 2024). A malignant cartilaginous matrix-producing mesenchymal neoplasm arising from the bone and soft tissue. "F-spondin 1 (SPON1), an extracellular matrix protein known for enhancing neuronal development, emerges as a potential player in chondrosarcoma." (PMID 38542153, 2024). "However, a compelling clue lies in the significantly lower levels of miR-525, a microRNA directly targeting SPON1, observed in chondrosarcoma patients." (PMID 38542153, 2024). "Interestingly, SPON1 has been shown to be upregulated in several cancers, including neuroblastoma and chondrosarcoma, and it has also been found to have a role in promoting neuroblastoma by leading high IL-6 expression through the MEKK/p38 MAPK/NF-κB–dependent pathway." (PMID 38716730, 2024).
Cognitive impairment (2 papers, 2020 to 2024). Abnormal cognition is characterized by deficits in thinking, reasoning, or remembering. "Additional markers of alterations in nerve tissue repair (SPON-1 and NFASC) were elevated in those with cognitive impairment and SCG3, suggestive of brain–gut axis disturbance, was elevated in gastrointestinal symptoms." (PMID 38589621, 2024).
colorectal cancer (2 papers, 2022). A primary or metastatic malignant neoplasm that affects the colon or rectum. "SPON1 was found to be downregulated in colorectal cancers (CRC) compared to healthy colorectal tissues, which was associated with a better OS in CRC patients." (PMID 36354023, 2022).
diabetes (2 papers, 2018 to 2024). "We observed evidence of colocalization for observed MR associations for SPON1, CCL15, and FSTL3 with multiple outcomes; for SVEP1 with HF; and for NRP1 with diabetes and CHD." (PMID 38225249, 2024).